CLDN11 (claudin 11)
Description:
Plays a major role in tight junction-specific obliteration of the intercellular space, through calcium-independent cell-adhesion activity.
Synonyms: OSP; OTM; HLD22
Tractability: Antibody: UniProt places it where antibodies can reach, with high confidence; its Gene Ontology location is reachable by antibodies, with high confidence; UniProt predicts a signal peptide or a membrane-spanning region.
Gene: Protein-coding gene on chromosome 3 (170,418,865 to 170,454,733, forward strand). Ensembl gene ENSG00000013297.
Subcellular location: Cell junction, tight junction; Cell membrane
Subcellular location (Human Protein Atlas): Cell Junctions; Lipid droplets
Pathways (Reactome):
Cell-Cell communication: Tight junction interactions
Gene Ontology:
Molecular function: identical protein binding; protein binding; structural molecule activity
Biological process: tight junction assembly; calcium-independent cell-cell adhesion; cell adhesion
Cellular component: axon; cell junction; neurofilament; plasma membrane; tight junction; bicellular tight junction; membrane
Genetic constraint (gnomAD): Loss-of-function variants: 1 observed, 13.65 expected, observed/expected ratio (o/e) 0.0733, 90% interval 0.025 to 0.35. The upper end of that interval is the gene's LOEUF score, 0.35, which puts it in group 1 of 6, group 1 being the genes least tolerant of losing a copy. Missense variants: 172 observed, 254.8 expected, observed/expected ratio (o/e) 0.68, 90% interval 0.6 to 0.77. Synonymous variants: 116 observed, 114.38 expected, observed/expected ratio (o/e) 1.01, 90% interval 0.87 to 1.18.
Gene-disease validity (ClinGen):
ClinGen rates the evidence that CLDN11 causes each of these diseases.
leukodystrophy, hypomyelinating, 22 (autosomal dominant): Moderate.
Homologues: Orthologues: chimpanzee CLDN11 (99% identical), macaque CLDN11 (98% identical), dog CLDN11 (97% identical), guinea pig CLDN11 (97% identical), pig CLDN11 (97% identical), rabbit CLDN11 (96% identical), mouse Cldn11 (94% identical), rat Cldn11 (94% identical), tropical clawed frog cldn11 (68% identical), zebrafish cldn11a (57% identical), zebrafish cldn11b (48% identical). Paralogues in human: CLDN1 (27% identical), CLDN19 (26% identical), CLDN5 (26% identical), CLDN7 (26% identical), CLDN18 (26% identical), CLDN14 (25% identical), CLDN3 (25% identical), CLDN15 (25% identical), CLDN10 (24% identical), CLDN17 (23% identical), CLDN20 (23% identical), CLDN9 (23% identical), and 10 more.
Diseases named in the same sentence as CLDN11 in open-access papers:
CLDN11 is named in the same sentence as 88 diseases in open-access papers, as found by Europe PMC text mining. Sharing a sentence is not in itself a finding about the gene and the disease. The quoted sentences say what the papers report.
gastric cancer (20 papers, 2009 to 2024). A primary or metastatic malignant neoplasm involving the stomach. "Further investigation into the mechanism underlying the abnormal expression of claudin-11, -23 in gastric cancers is necessary." (PMID 28350854, 2017). "We analyzed the associations between claudin-11, -23 expression and clinicopathologic parameters in gastric cancer." (PMID 28350854, 2017). "DNA hypermethylation is associated with the downregulation of CLDN11 in gastric cancer cells and CLDN7 in breast cancer cells." (PMID 24009024, 2013). "In relation to gastric cancer, the hypermethylation of the Claudin-11 promoter has been associated with increased invasive potential, and the hypermethylation of the Claudin-3 promoter is considered a predictor of poor prognosis in advanced gastric adenocarcinoma." (PMID 39296813, 2021). "our analysis implied that DNA hypomethylation may lead to induce the RDH13 and UCHL1 expression in gastric cancer, whereas DNA hypermethylation is able to cause decreasing expression of CLDN11 in gastric groups." (PMID 34322159, 2021). "Finally, we found also a decreased expression of CLDN11, whose silencing is associated with increased invasiveness of gastric cancer cells." (PMID 34012923, 2021). "The underlying mechanisms of the abnormal expression of claudin-11, -23 in gastric cancer remain unclear." (PMID 28350854, 2017). "As for analysis of clinicopathologic parameters of gastric cancer, logistic multiple regression indicated that claudin-11 was significantly associated with sex, smoking, alcohol, H. pylori infection and Borrmann classification while claudin-23 was significantly associated with vessel cancer embolus." (PMID 28350854, 2017). "Reduced CLDN11 expression is associated with increased invasiveness of gastric cancer cells." (PMID 24009024, 2013). "Claudin-11 (CLDN11) has been reported to be upregulated in breast carcinoma, squamous cell lung cancer, and gastric cancer." (PMID 38540693, 2024). "Our bisulfite sequencing analysis demonstrated that the hypermethylated CLDN11 promoter region is located at − 137 to + 405, similar to previously reported differentially hypermethylated region in gastric cancer (− 104 to + 4) and in melanoma (+ 144 to + 249)." (PMID 29747653, 2018). "CLDN11 is hypermethylated and silenced in bladder cancer, gastric cancer, oral leukoplakias and malignant melanoma." (PMID 29747653, 2018). "In summary, downregulation of claudin-11, -23 in gastric cancer correlated with some clinicopathologic features; in particular, claudin-23 showed potential for development as a prognosticator of patient survival." (PMID 28350854, 2017). "In this study, we compared the expression of claudin-11, -23 in gastric cancer, atrophic gastritis, and superficial gastritis." (PMID 28350854, 2017). "In this study, we focused on two major members of the claudin family, claudin-11, -23, and examined their expression in gastric cancer, atrophic gastritis, and superficial gastritis." (PMID 28350854, 2017). "The results indicated that the expression of claudin-11 and 23 was significantly higher in superficial gastritis than that in atrophic gastritis and gastric cancer." (PMID 28350854, 2017). "We further investigated the relationships between claudin-11, -23 expression and the prognosis of gastric cancer patients." (PMID 28350854, 2017). "We aimed to investigate expression of claudin-11, -23 in different gastric tissues and its relationship with clinicopathologic parameters and prognosis of gastric cancer." (PMID 28350854, 2017). "However, in our present work the cytoplasmic staining of claudin-11 was strong in gastric cancer tissues and weak in adjacent tissues, reveals that claudin-11 may be a positive diagnostic marker in gastric cancer which was different with claudin-2 and claudin-6." (PMID 23919729, 2013). "In contrast, the positive expression rates of claudin-11 in gastric cancer tissues and gastric cancer adjacent tissues were 80% and 46% (P = 0.004 < 0.01)." (PMID 23919729, 2013).
gastric cancer (continued). "We conclude that claudin-11 expression is significantly higher in gastric cancer samples than in histologically normal gastric tissue." (PMID 23919729, 2013). "The cytoplasmic staining of claudin-11 was strong in gastric cancer tissues and weak in adjacent tissues." (PMID 23919729, 2013). "The CLDN11 promoter region was also hypermethylated in all gastric cancer cell lines tested relative to immortalized normal gastric epithelial cells." (PMID 19956721, 2009). "In the present study, we report that claudin-11 (CLDN11) is silenced in gastric cancer via hypermethylation of its promoter region." (PMID 19956721, 2009). "Similarly, miR-421 promoted the proliferation and metastasis of gastric cancer cells by targeting claudin-11." (PMID 33714203, 2021). "And it has been studied that gene CLDN11 (claudin-11) has been shown to be silenced in gastric cancer via hypermethylation of its promoter region, and this hypermethylation is significantly correlated with downregulation of CLDN11 expression vs. normal tissues." (PMID 34322159, 2021). "Collectively, all of the results above illustrate that CLDN11 expression may be repressed by hypermethylation in promoter region, which induces the gastric cancer." (PMID 34322159, 2021). "Moreover, we investigated the relationships between expression of claudin-11, -23 and clinicopathologic parameters and survival in gastric cancer." (PMID 28350854, 2017). "In addition, the relationship between the expression of claudin-11, -23 and the biologic behavior and prognosis of gastric cancer remains elusive." (PMID 28350854, 2017). "In conclusion, the expression of claudin-11, -23 was remarkably downregulated in gastric cancer." (PMID 28350854, 2017). "It has been reported increased expression of CLDN11 in gastric cancer." (PMID 29221203, 2017). "We further investigated the relationship between the expression of claudin-11, -23 and the clinicopathologic parameters and prognosis of gastric cancer to elucidate the potential roles of claudin-11, -23 in the occurrence, progression, and prognosis of gastric cancer." (PMID 28350854, 2017). "The results suggested that the expression of claudin-11 in superficial gastritis was higher than that in atrophic gastritis (P = 7.63*10−6), and the expression in atrophic gastritis was significantly higher than that in gastric cancer (P = 9.85*10−5)." (PMID 28350854, 2017). "Claudin-11 was expressed in 80.0% (32/40) of gastric cancer tissues." (PMID 23919729, 2013). "Thus in our study, the expression of claudin-2, and claudin-6 was down regulated in gastric cancer tissue while the expression of claudin-11 was up regulated." (PMID 23919729, 2013). "Analyses of paired gastric cancers and adjacent normal gastric tissues revealed hypermethylation of the CLDN11 promoter region in gastric cancers, and this hypermethylation was significantly correlated with downregulation of CLDN11 expression vs. normal tissues." (PMID 19956721, 2009). "We revealed that RDH13, CLDN11, TMTC1, UCHL1, and FOXP2 can serve as predictive biomarkers for gastric cancer treatment and the promoter methylation level of these five genes in serum could have prognostic and diagnostic functions in gastric cancer patients." (PMID 34322159, 2021). "Our results showed that claudin-11, -23 were closely related to the occurrence and progression of gastric cancer, and may therefore serve as potential biomarkers for the diagnosis and prognosis of gastric cancer." (PMID 28350854, 2017). "Therefore, whether claudin-11, -23 participate in the occurrence and progression of gastric cancer and their relationship with the prognosis of patients with gastric cancer should be further investigated." (PMID 28350854, 2017). "The authors found a subgroup of cells between the metastatic group and primary group and discovered some gastric cancer lymph node metastasis marker genes (ERBB2, CLDN11, and CDK12), as well as potential gastric cancer evolution-driving genes (FOS and JUN)." (PMID 37612741, 2023).
gastric cancer (continued). "Hypermethylated CLDN11 can be utilized as a biomarker for the early detection of CRC melanoma, and gastric cancer." (PMID 35281827, 2022). "Further, we identified 5 prognostic genes (RDH13, CLDN11, TMTC1, UCHL1, and FOXP2) in gastric cancer." (PMID 34322159, 2021). "Claudin-11 was found to be down-regulated in GC tissue, furthermore, silencing of CLDN11 in gastric cancer cell line was responsible for increased motility and invasiveness." (PMID 34822542, 2021). "An analysis of gastric cancer lymph node metastasis revealed the presence of ERBB2, CLDN11 and CDK12, as markers of lymph node metastasis, which may contribute to lymph node metastasis in gastric cancer." (PMID 37305583, 2023). "We further used immunohistochemistry to compare the expression of claudin-11, -23 between gastric cancer and adjacent non-tumor tissues, including superficial gastritis and atrophic gastritis." (PMID 28350854, 2017). "We also used an immunohistochemical method to compare expression of claudin-11, -23 between non-cancer individuals with superficial gastritis, atrophic gastritis, and gastric cancer." (PMID 28350854, 2017). "The expression of claudin-23 was significantly lower in atrophic gastritis than that in gastric cancer, but no obviously difference was observed for claudin-11." (PMID 28350854, 2017). "In addition, the expression of claudin-11 in gastric cancer with H. pylori infection was significantly higher than that in that without H. pylori infection (58.3% vs. 81.3%, P = 0.014), indicating that infection with H. pylori might affect the expression of claudin-11." (PMID 28350854, 2017). "The present work infers that the expression altered of claudin-2, claudin-6, and claudin-11 between human gastric cancers and adjacent non-neoplastic tissues and does not correlate with their clinical behavior." (PMID 23919729, 2013). "Treatment of CLDN11-nonexpressing gastric cancer cells with 5-aza-2′-deoxycytidine restored CLDN11 expression." (PMID 19956721, 2009). "In this study, we used real-time PCR, western blotting, and immunohistochemical methods to detect the expression of claudin-11, -23 in different gastric diseases, including superficial gastritis, atrophic gastritis, gastric cancer, and adjacent non-tumor tissues." (PMID 28350854, 2017). "Our results showed that expression of claudin-11 in superficial gastritis was higher than that in atrophic gastritis and gastric cancer (P = 1.10*10−9), but there was no obvious difference between atrophic gastritis and gastric cancer (P = 0.076)." (PMID 28350854, 2017). "Levels of CLDN11 methylation and mRNA expression were measured in primary gastric cancer tissues, noncancerous gastric mucosae, and cell lines of gastric origin using quantitative methylation-specific PCR (qMSP) and quantitative reverse transcriptase-PCR (qRT-PCR), respectively." (PMID 19956721, 2009).
Infertility (10 papers, 2016 to 2023). "Claudin-11 is a key component of tight junction (TJ) barrier and closely related to spermatogenesis, and its deficiency caused infertility." (PMID 31142324, 2019). "The infertility is restricted to males; Cldn11 null females are able to produce litter sizes comparable to controls." (PMID 38298375, 2023). "Klinefelter syndrome (KS) is the most frequent hereditary cause of infertility in males; the expression of the BTB proteins connexin-43 and claudin-11 is drastically decreased in KS patients." (PMID 36071829, 2022). "Changed localization of claudin-11 from membrane to cytoplasm was observed in Sertoli cells in infertile men." (PMID 32197343, 2020). "The authors of the study also reported that in testes of men suffering from various degrees of infertility distinct small changes in the immunoreactive pattern of claudin-11 occur." (PMID 27849015, 2016). "The disorganization of claudin-11 expression in Sertoli cells could be one of the factors affecting spermatogenesis in infertile men." (PMID 36835702, 2023). "Claudin-11 is known to be regulated hormonally, and its knockout models result in infertility." (PMID 32197343, 2020). "Interestingly, claudin-11 KO mice also develop male sterility, coinciding with infertility known from adult SCCx43KO mice." (PMID 32328805, 2020). "Interestingly, claudin-11 is the sole essential claudin for spermatogenesis, as its absence in knockout mice leads to infertility, whereas loss of claudin-1, -3, -12, or -13 does not affect fertility." (PMID 38298375, 2023). "Accordingly, CLDN11/OSP knockout mice exhibit both neurological and reproductive disorders, including slow nerve conduction velocity and infertility in male mice due to deficits of the parallel-array TJ strands in the CNS myelin and Sertoli cells." (PMID 31500278, 2019). "A later study showed that Cldn11-null mice were infertile due to the lack of spermatozoa since germ cells were unable to differentiate beyond the spermatocyte stage." (PMID 37759514, 2023). "Finally, the development of VC-mediated infertility (VMI) may be facilitated by abnormal permeability of proteins, such as claudin-11, that constitute the blood-testis barrier (BTB)." (PMID 34531872, 2021).
breast carcinoma (9 papers, 2013 to 2025). "Alternatively, the loss of claudin-11 (also known as oligodendrocyte-specific protein) was shown to impair migration of primary oligodendrocytes and loss of claudin-5 in the breast cancer cell line MDA-MB-231 cells inhibited cell motility." (PMID 23521713, 2013). "Increased expression of CLDN11 has also been linked to better overall breast cancer survival." (PMID 39796775, 2025). "Collectively, these findings demonstrated that CLDN11 was a direct target of miR-205 in breast cancer cells." (PMID 33971623, 2021). "The results indicated that overexpression of miR-205 significantly reduced the mRNA level of CLDN11 in breast cancer cells." (PMID 33971623, 2021). "Notably, reduced expression of MCAM and CLDN11 in breast cancer correlated with poor overall survival and relapse-free survival." (PMID 40083695, 2025). "Taken together, these findings indicated the tumor-suppressive role of miR-205 in breast cancer by targeting CLDN11; implying miR-205 may serve as a novel therapeutic target for breast cancer." (PMID 33971623, 2021). "Our previous work demonstrated that CLDN11 may function as a prognostic biomarker and could serve as an important new therapeutic target for human breast cancer." (PMID 33971623, 2021). "These additional markers were identified in only one article within our systematic review, reporting the downregulation of MCAM (CD146) in glioblastoma 24, CLDN11 (claudin 11) in colon cancer 82, and TJP2 in melanoma and breast cancer." (PMID 40083695, 2025). "For example, CLDN11 and CLDN14 are correlated with prognostic values in human breast carcinoma." (PMID 37799140, 2023). "Mechanistically, claudin 11 (CLDN11) was found to be the direct target of miR-205; the function of miR-205 could be exerted via down regulation of the target gene CLDN11 in breast cancer cells." (PMID 33971623, 2021).
deafness (7 papers, 2007 to 2024). An inherited or acquired condition characterized by the complete loss of the ability to hear from one or both ears. "Loss of Cldn11, which encodes the CLDN11 protein that is expressed in tight junctions of SV basal cells, has been shown to result in deafness and reduced EP in Cldn11 null mice." (PMID 34566577, 2021). "In fact, mutation of the Claudin-14 gene was reported to cause human hereditary deafness and Claudin-11 null mice exhibit severe deafness associated with low endocochlear potential." (PMID 18154640, 2007). "Claudin 11 (Cldn11), a tight junction protein expressed in SV basal cells, is critical to this function as demonstrated by deafness and low EP in Cldn11 null mice." (PMID 31920542, 2019). "In addition to myelin-related alterations, Cldn11 null mice present with two other distinct phenotypes: deafness and sterility." (PMID 38298375, 2023). "Together, our data show the Tg(Cldn11)605Gow transgene rescues deafness and male infertility in Cldn11−/− mice, but is not expressed by oligodendrocytes." (PMID 29491447, 2018). "The Cldn11 gene, which encodes Claudin-11, has not, thus far, been identified as a deafness gene while mutations in the genes encoding Claudin-14 (DFNB29) and Claudin-9 cause autosomal recessive deafness in humans and mice." (PMID 28848383, 2017). "The absence of claudin-11 compromises endocochlear potential and mice present with deafness." (PMID 38298375, 2023). "This hypothesis was confirmed by in vivo experiments showing that Claudin-11 null mice exhibit severe deafness and a low EP but no other morphological changes." (PMID 28848383, 2017).